HMGB1 (high mobility group box 1)
Diseases named in the same sentence as HMGB1 in open-access papers (continued):
Sharing a sentence is not in itself a finding about the gene and the disease.
pneumococcal meningitis (6 papers, 2017 to 2024). An acute purulent infection of the meninges and subarachnoid space caused by Streptococcus pneumoniae, most prevalent in children and adults over the age of 60. "Nrf2 or HO-1 gene-deficient mice with pneumococcal meningitis showed significantly higher levels of HMGB1 and iNOS." (PMID 34545298, 2021). "In this study, we evaluated if paquinimod, an MRP14-inhibitor, and an anti-HMGB1 antibody can improve clinical outcome as adjunctive therapeutics in pneumococcal meningitis." (PMID 29096648, 2017). "In one study, high mobility group box 1 was suggested as such a target due to its role in the development of pneumococcal meningitis and its ability to elicit strong inflammatory response in the injured brain cells." (PMID 28469997, 2017). "HMGB1 inhibition has been proposed as adjunctive therapy for pneumococcal meningitis." (PMID 34271850, 2021). "(iii) Combining the anti-HMGB1 treatment with dexamethasone, the standard adjuvant treatment of pneumococcal meningitis, neither improved nor diminished the effect of the former." (PMID 29096648, 2017). "Evidence suggests that paquinimod, an MRP14-inhibitor, and an anti-HMGB1 antibody can improve clinical outcome as adjunctive therapeutics in a mouse model of pneumococcal meningitis, and adjunctive inhibition of MRP14 or HMGB1 reduces mortality in mice with pneumococcal meningitis." (PMID 33114371, 2020).
retinal detachment (6 papers, 2011 to 2022). An eye emergency condition which may lead to blindness if left untreated. "The DAMPs such as S100, HMGB1, and histones were found to be upregulated in the vitreous of the retinal detachment patients." (PMID 35269741, 2022). "There is also an increase in HMGB1 in the vitreous humor of patients with proliferative DR and retinal detachment compared to patients with retinal detachment alone." (PMID 35269741, 2022). "This study thus demonstrates the important role of HMGB1 in the response of PRs to retinal detachment and confirms the cell-autonomous functions of HMGB1 in promoting PR cell survival." (PMID 34440779, 2021). "In vivo studies showed that induction of retinal detachment in rats induced upregulation of HMGB1 in both the photoreceptors and the other retinal cells and release of HMGB1 in the subretinal space." (PMID 21850157, 2011). "In addition, RD models with photoreceptor death are reported to show increased levels of HMGB1 in a rat retinal detachment model and in human eyes with retinal detachment as well as in an RD model induced by dsRNA injection." (PMID 31379505, 2019). "In addition, increased level of HMGB1 has been found in a rat retinal detachment model and in human eyes with retinal detachment, in which photoreceptors mainly die." (PMID 31379505, 2019). "Interestingly, Arimura and others showed that the vitreous level of high-mobility group box 1 (HMGB1) is increased in human eyes with retinal detachment." (PMID 21670490, 2011).
sarcopenia (6 papers, 2022 to 2025). Progressive decline in muscle mass due to aging which results in decreased functional capacity of muscles. "HMGB1 has been implicated in cancer-associated sarcopenia, cancer-related cardiac dysfunction, and skeletal muscle aging." (PMID 40699723, 2025). "HMGB1 has been implicated in inducing autophagy in skeletal muscles, leading to sarcopenia." (PMID 38731953, 2024). "Additionally, HMGB1 has been shown to exacerbate cancer-associated sarcopenia." (PMID 40699723, 2025). "Future investigations into whether cytokines other than HMGB1 are involved in BCAA metabolic disorders will be useful in elucidating the mechanism of cancer sarcopenia." (PMID 40699723, 2025). "Examining the effects of CT on cancer sarcopenia, CT reduced skeletal muscle volume and muscle maturity by reducing oxidative stress, suppressing autophagy and apoptosis, improving oxidative phosphorylation, and suppressing HMGB1 production." (PMID 39796128, 2024). "HMGB1 is a cytokine that induces autophagy in skeletal muscle, is increased in the blood of cancer patients, and plays an important role in the development of sarcopenia." (PMID 39796128, 2024). "HMGB1 is upregulated in muscle inflammation, and circulating levels of the proinflammatory cytokine interleukin-18 (IL-18) are upregulated in patients with sarcopenia, a muscle-wasting disease." (PMID 36497194, 2022).
small cell lung carcinoma (6 papers, 2021 to 2025). Small cell lung cancer (SCLC) is a highly aggressive malignant neoplasm, accounting for 10-15% of lung cancer cases, characterized byrapid growth, and early metastasis. "A study identified a strong correlation between high-mobility group box protein B1 (HMGB1) and chemoresistance in small-cell lung cancer (SCLC)." (PMID 39858036, 2025). "There were also no appreciable differences in lung small cell carcinomas regarding age, gender, smoking status, or HMGB1 concentration." (PMID 37518006, 2023). "HMGB1 also induces PARP1 self-modification, which promotes the interaction of PARP1 with LC3, which in turn triggers autophagy and, finally, chemotherapy resistance in small-cell lung cancer; therefore, HMGB1 may be a predictive biomarker of PARP1 response in small-cell lung cancer patients." (PMID 41296391, 2025).
Splenomegaly (6 papers, 2013 to 2020). Abnormal increased size of the spleen. "We also measured plasma levels of GM-CSF, G-CSF, HMGB-1 and pentraxin 3, because they have all been linked to splenomegaly." (PMID 32824440, 2020). "The kinetics of the onset of splenomegaly coincided with the appearance of C23–45 disulphide-linked HMGB1 (C23–45 HMGB1) and was attenuated by administration of anti-HMGB1 antibodies." (PMID 23808943, 2013). "We also measured other cytokines that might be involved in splenomegaly during cancer cachexia, including granulocyte-macrophage colony-stimulating factor (GM-CSF), granulocyte-colony stimulating factor (G-CSF) and HMGB-1." (PMID 32824440, 2020). "Thus, together with previous results, our findings suggest that C23–45 HMGB1 is a necessary and sufficient mediator of splenomegaly, leucocytosis and enhanced endotoxin responses in splenocytes in murine sepsis survivor syndrome." (PMID 23808943, 2013). "Unfortunately, we did not observe any effects of PM01183 that could explain the delay in splenomegaly, with the exception of a tendency to reduced HMGB-1 levels in PM-treated C26-mice that was not significant." (PMID 32824440, 2020).
ulcer (6 papers, 2009 to 2025). "Additionally, NLRP3 levels were markedly higher in the ulcer group, indicating enhanced inflammasome activation closely associated with increased HMGB1 levels." (PMID 40563542, 2025). "Thus, TLR4 and RAGE play critical roles in pathogenesis mediated by the HMGB1-associated pathway, including the pathway in our ulcer healing model." (PMID 24244627, 2013). "In the ulcer group, HMGB1 levels were significantly increased relative to the control group, indicating its function as a critical pro-inflammatory mediator." (PMID 40563542, 2025). "Treatment with OMP or OMP-NS resulted in significant reductions in HMGB1 levels relative to the ulcer group, demonstrating their effectiveness in mitigating the inflammatory response." (PMID 40563542, 2025). "HMGB1 and Nuclear factor kappa (NF-B) expression, IL-1β and Nrf2 contents showed an increase along with ulcer development, concurrent with an increase in immunohistochemical TLR-4 level." (PMID 37371993, 2023). "Mice were administered rHMGB1 or anti-HMGB1 antibody intraperitoneally following the induction of ulcer." (PMID 24244627, 2013). "The induction of ulcer increased the immunohistochemical staining of cytoplasmic HMGB1 and elevated serum HMGB1 levels." (PMID 24244627, 2013). "Gastric HMGB1 mRNA levels increased during ulcer healing, suggesting that inflammatory cells produce and release HMGB1." (PMID 24244627, 2013). "We also investigated which receptor among TLR2, TLR4, or RAGE mediates HMGB1’s effects on ulcer healing." (PMID 24244627, 2013). "In contrast, administration of anti-HMGB1 antibody promoted ulcer healing and reduced MPO activity and TNFα expression." (PMID 24244627, 2013). "Conversely, immunoneutralization of HMGB1 or inhibiting the release of HMGB1 promotes ulcer healing while reducing TNFα expression and MPO activity." (PMID 24244627, 2013). "HMGB1 mRNA levels were almost constant during the examination period, whereas the serum levels of HMGB1 dropped to normal levels 6 days after the induction of ulcer." (PMID 24244627, 2013). "Thus, we expect that the deleterious of HMGB1 on ulcer healing would be more prominent in H. pylori-infected patients." (PMID 24244627, 2013). "Furthermore, the administration of ethyl pyruvate, an inhibitor of HMGB1 release, markedly promoted ulcer healing, compared with vehicle treatment." (PMID 24244627, 2013). "Additionally, TLR4 and RAGE deficiency promotes ulcer healing, and exogenous HMGB1 fails to delay ulcer healing in TLR4 KO and RAGE KO mice." (PMID 24244627, 2013). "A direct comparison between the ulcer + OMP and ulcer + OMP-NS groups revealed that the OMP-NS formulation significantly decreased levels of HMGB1, NLRP3, NF-κB, TLR-2, MyD88, IL-1β, IL-6, and TNF-α." (PMID 40563542, 2025). "Our findings corroborate earlier research indicating that OMP, used as a reference drug, significantly diminished the levels of HMGB1, NF-κB p65, and NLRP3 in comparison to the ulcer group and substantially reduced the levels of IL-1β, IL-6, and TNF-α in gastric mucosa." (PMID 40563542, 2025). "In the normal group, the HMGB1 levels were slightly higher in ulcer group than non-ulcer group, but the difference was not statistically significant (p > 0.05)." (PMID 19476625, 2009). "In TLR4 KO and RAGE KO mice, exogenous HMGB1 did not affect ulcer healing and TNFα expression." (PMID 24244627, 2013).
uveitis (6 papers, 2012 to 2023). An inflammatory process affecting a part of or the entire uvea. "Although this represents the first indication of HMGB1 and CXCL12 pathological expression in uveitis, redox status of HMGB1 and therefore heterocomplex formation remains to be proven." (PMID 37251376, 2023). "Uveitis was evaluated in the IRBP-specific T cell transferred Faslpr mice after recombinant HMGB1 was restored within the eye and in the IRBP-specific T cell transferred Wt mice after they were treated with a Fas antagonist (Met12)." (PMID 26394985, 2015). "High-mobility group box 1 (HMGB1) proteins are another class of molecules that have been identified in high concentrations in endophthalmitis and experimental uveitis." (PMID 22973073, 2012). "HMGB1 plays an important role in Behcet's disease, one of the forms of uveitis." (PMID 30473885, 2018). "RIP2 is also involved in HMGB1 release which is deeply related with Fas in uveitis." (PMID 30473885, 2018). "This suggests the active involvement of the HMGB1-Fas-RIP2 axis in uveitis." (PMID 30473885, 2018). "However, how HMGB1 is involved in the pathogenesis of effector phase of uveitis is not clear." (PMID 28261206, 2017).
Alcohol Use Disorder (5 papers, 2018 to 2026). "Both alcohol use disorder (AUD) and AD share common underlying neuropathology, including proinflammatory high-mobility group box 1 (HMGB1)-mediated neuroimmune signaling and basal forebrain cholinergic neuron degeneration." (PMID 40046779, 2025).
autoimmune thyroiditis (5 papers, 2021 to 2026). "Studies have shown that HMGB1 is involved in the pathogenesis of autoimmune thyroiditis and other chronic diseases by augmenting inflammation signaling and inflammatory infiltration." (PMID 33776579, 2021). "HMGB1 may also be involved in the pathogenesis of Autoimmune Thyroid Disease (AITD)." (PMID 37667233, 2023). "Mudanpi is a key specific component in DZXY, and its active ingredient, paeonol (PAE), has been proven to promote the Th17/Treg balance in AIT rats by inhibiting the HMGB1/RAGE pathway, thereby protecting against pathological damage in autoimmune thyroid rats." (PMID 40584613, 2025).
bone fracture (5 papers, 2017 to 2023). "High mobility group box 1 (HMGB1), which is in the inflammatory microenvironment of bone fracture, was reported to promote h-BMSC osteo-differentiation by binding to TLR2/4 and activating the p38 MAPK signaling pathway." (PMID 37941898, 2023). "Bone fracture also promotes the release of damage-associated molecular patterns (DAMPS), such as HMGB-1 or heat shock protein 70 (HSP-70), and alarmin cytokines such as interleukin-33 (IL-33)." (PMID 34956079, 2021). "The follow-up experiment demonstrated that HMGB1 increased immediately after bone fracture and is an important mediator for post-bone fracture cognitive dysfunction." (PMID 29786644, 2018). "Further probing the potential overlap of systemic and central inflammatory pathways, which could contribute to bone fracture-induced cognitive pathology, the authors employed a monoclonal antibody (mAb) against HMGB1." (PMID 29786644, 2018). "However, the alterations in cardiac glucose and fatty acid transporters following bone fracture were recently demonstrated to be induced by pro-inflammatory mediators such as HMGB1, IL-1β, IL-6 and TNF, all of which have been shown to be elevated following hip fracture in the present study." (PMID 36131923, 2022). "The CRKF procedure may be a good solution for the treatment of bone fractures, as damaged associated molecular patterns – HMGB-1 and HSP-70 – did not significantly differ 12-14 hours after the approach was applied as compared to the control group." (PMID 34956079, 2021). "Therefore, HMGB1 plays a key role in initiating the inflammatory cascade after bone fracture." (PMID 29786644, 2018).
brain inflammation (5 papers, 2016 to 2025). "Therefore, therapies with anti-HMGB1 mAb and inhibitors of HMGB1 release may provide novel approaches to the treatment of brain inflammatory diseases associated with BBB disruption." (PMID 33321691, 2020). "This pathway might represent an important flexible mechanism to regulate the activity of HMGB-1, and potentially provides a candidate for modifying and augmenting the protective effects in astrocytes in response to LPS preconditioning after brain inflammation or injuries." (PMID 26115623, 2016). "In the present review, we focus on the dynamics of HMGB1 translocation in different disease conditions in the CNS and discuss the functional roles of extracellular HMGB1 in BBB disruption and brain inflammation." (PMID 33321691, 2020). "Together, these results indicated that alarmin HMGB1 mediates potentiation of LPS function, exacerbating TLR4-dependent systemic and brain inflammation in a rat PSI model and there is a positive-feedback loop between augmentation of LPS function by HMGB1 and subsequent HMGB1 release/serum." (PMID 29555931, 2018). "Peripheral surgery may disrupt the BBB via complement activation and pro-inflammatory cytokines, such as TNF-α and high mobility group box-1 (HMGB1), which promotes brain inflammation." (PMID 30501622, 2018). "In addition to this, HMGB1 mediates enhanced pro-inflammatory effects of lipopolysaccharides and exacerbates TLR4-dependent systemic and brain inflammation, and there is a positive feedback loop between the enhancement of LPS function by HMGB1 and the subsequent release of HMGB1." (PMID 38740617, 2025).
breast tumor (5 papers, 2016 to 2021). "Although the presence of DCs within breast tumors has been associated with either anti-tumor or pro-tumor effects, the presence of DCs activated by the release of HMGB1 has been unequivocally correlated with the recruitment of T-lymphocytes recognizing tumor-associated antigens." (PMID 26980746, 2016). "The supernatant from MCF-7 breast tumor cells is rich in HMGB1 and skews bone marrow progenitors into MDSCs, a phenomenon which is abrogated by treatment with ethyl pyruvate or anti-HMGB1 antibody." (PMID 31379812, 2019). "To do so, we had to deal with the fact that CCND1 in lung and breast tumour cell lines, EZR (Ezrin) and HMGB1 in normal Schwann cells, were the only published nuclear targets of ErbB3." (PMID 27191720, 2016).
chronic hepatitis B (5 papers, 2011 to 2021). "Previous studies have shown that HMGB1 regulated Treg/IL17 ratio in patients with chronic hepatitis B, in which HMGB1 was significantly higher and induced Th17 cells but suppressed Tregs via TLR4 and IL6 pathway." (PMID 33679792, 2021). "A study on the detection of hepatocyte death biomarkers in patients with hepatitis B virus-related ACLF (HBV-ACLF) finds that the serum HMGB1 level of HBV-ACLF patients is significantly higher than that of healthy controls and chronic hepatitis B (CHB) patients." (PMID 34904016, 2021).
clear cell renal cell carcinoma (5 papers, 2014 to 2025). "HMGB1 mediated the progression of clear cell renal cell carcinoma via ERK1/2 activation, which was partially mediated by RAGE." (PMID 24705787, 2014). "HMGB1, RAGE, and autophagy proteins LC3, Beclin-1, and PI3K are significantly increased in clear cell renal cell carcinoma." (PMID 38529373, 2024). "The binding of HMGB1 to RAGE initiates intracellular signaling and activates ERK, leading to increased migration and invasion of clear cell renal cell carcinoma cells (RCCC)." (PMID 38529373, 2024). "Higher coexpression of HMGB1 and RAGE in clear cell renal cell carcinoma positively correlated with tumor size, grade and clinical stage." (PMID 24705787, 2014).
colorectal tumor (5 papers, 2015 to 2023). "The CC3 and HMGB1 protein expression in colorectal tumor and peritumoral tissues were detected by immunohistochemistry and their correlation with prognosis were analyzed." (PMID 25986235, 2015). "Moreover, the cytokine-like factor HMGB1 is highly abundant in colorectal tumor cells, and can be released into the circulation by activated immune cells, and by passive leakage from necrotic (tumor) cells." (PMID 29675023, 2018). "Interestedly, immunohistochemistry staining showed that positive HMGB1, CC3, and Ki67 expression were significantly higher in colorectal tumor tissues than in peritumoral tissues (p <0.01)." (PMID 25986235, 2015). "The irradiated colorectal tumor cells underwent apoptosis and necrosis and produced CC3 in tumor cells and HMGB1 in the supernatant of cultured cells." (PMID 25986235, 2015). "Since HMGB1 accelerates cell growth, invasion, and angiogenesis in cancer tissues, CD45RO + lymphocytes might subsequently suppress the proliferation and migration of colorectal tumor cells." (PMID 36765348, 2023).
coronary artery stenosis (5 papers, 2012 to 2023). "Moreover high HMGB-1 serum levels have been reported be associated with CAD in patients with and without T2D and they were gradually correlated with the severity of coronary artery stenosis." (PMID 28789654, 2017).